FTO (FTO alpha-ketoglutarate dependent dioxygenase)
Diseases named in the same sentence as FTO in open-access papers (continued):
Sharing a sentence is not in itself a finding about the gene and the disease.
colorectal cancer (continued). "FTO rs9939609 polymorphism may influence both dietary intake and risk of colorectal cancer, according to some studies." (PMID 37545585, 2023). "Furthermore, FTO functioned as a tumor suppressor in colorectal cancer by inhibiting metastasis-associated protein 1 (MTA1) expression in an m6A-dependent manner." (PMID 35217651, 2022). "These evidence indicates that leptin could be a possible intermediary contributing to the association between the FTO rs9939609 polymorphism and colorectal cancer." (PMID 34650918, 2021). "Research has shown that increased levels of FTO enhance both PKM2 protein expression and the intensity of fluorescence staining for PKM2 in the nucleus, indicating that FTO is vital in the advancement of colorectal cancer through the regulation of PKM2." (PMID 41311582, 2025). "For instance, in colorectal cancer, overexpression of FTO and ALKBH5 suppresses proliferation both in vitro and in vivo, whereas their silencing enhances tumor growth." (PMID 41141648, 2025). "Hypoxia was observed to enhance the degree of FTO ubiquitination, with K216 serving as the primary location of FTO ubiquitination in colorectal cancer cells." (PMID 40919129, 2025). "Cytoplasmic FTO inhibits cancer stem cell (CSC) capabilities in colorectal cancer via its m6Am demethylase activity." (PMID 39192357, 2024). "In summary, we identified FTO as a potential oncogene in colorectal cancer cells and we demonstrated that targeting FTO significantly suppressed cancer cell proliferation, migration and invasion in vitro and tumor progression in vivo." (PMID 36874096, 2023). "To study the role of FTO in colorectal cancer, we used Lentivirus-mediated shRNA targeting FTO to inhibit FTO expression." (PMID 36874096, 2023). "While in the cytoplasm, FTO can dynamically regulate m6A modifications to contribute to the stemness of colorectal cancer cells and influence tumor drug resistance." (PMID 35614935, 2022). "FTO is upregulated in colorectal cancer and interacts with MYC to accelerate cell proliferation and migration." (PMID 35186927, 2022). "FTO gene was reported to be a potential target gene for microRNA-1,266 which influence the proliferation of colorectal cancer cell lines." (PMID 36263301, 2022). "This parameter is even more critical in the context of colorectal cancer, where a fraction of FTO relocates from the nucleus to the cytoplasm at an early stage of the disease." (PMID 33741917, 2021). "Fat mass and obesity-associated protein (FTO), an N6-methyladenosine (m6A) demethylase, participates in tumor progression and metastasis in many malignancies, but its role in colorectal cancer (CRC) is still unclear." (PMID 34218271, 2021). "Overall, our findings revealed a critical role of FTO as a predictor of metastasis and recurrence of colorectal cancer and elucidated a new epigenetic mechanism through which the hypoxic tumor microenvironment promotes CRC metastasis." (PMID 34218271, 2021). "This suggests that FTO-mediated m6Am demethylation takes place in the cytoplasm in colorectal cancer cell lines." (PMID 33741917, 2021). "We show that decreased FTO activity plays a critical role in colorectal cancer by enhancing CSC properties including sphere forming, in vivo tumorigenesis, and chemoresistance." (PMID 33741917, 2021). "For example, low miR-1266 expression promotes colorectal cancer progression by regulating demethylase FTO." (PMID 34950253, 2021). "Our study addresses the specific function of FTO in recently established colorectal cancer cell lines with a focus on CSC phenotype." (PMID 33741917, 2021). "Altogether, these observations established a first connecting thread between FTO-mediated m6Am dynamics and the acquisition of cancer stem ability in colorectal cancer." (PMID 33741917, 2021). "In colorectal cancer cell lines, FTO activity displays a remarkable selectivity for cap-m6Am, which concurs with its presence in the cytoplasm." (PMID 33741917, 2021).
colorectal cancer (continued). "On the same trend, our data support an anti-oncogenic role of FTO in colorectal cancer, emphasizing the importance of tissular context." (PMID 33741917, 2021). "Similarly, FTO overexpression enhanced chemoresistance in colorectal cancer by modulating SIVA1-mediated apoptosis." (PMID 39990672, 2025). "For example, in breast tumors, FTO promotes tumor progression by inhibiting BNIP3, whereas another study reported that FTO suppresses metastasis by demethylating the mRNA of metastasis-associated protein 1 in colorectal cancer." (PMID 40819127, 2025). "Recent research has shown that FTO acts as a preventative in colorectal cancer." (PMID 40919129, 2025). "FTO exhibits overexpression in both primary and 5-FU-resistant colorectal cancer." (PMID 40986143, 2025). "Studies have shown that FTO protein levels are downregulated in colorectal cancer tissues." (PMID 39192357, 2024). "We demonstrated that knockdown of FTO decreased cell proliferation, migration, invasion in vitro and suppressed tumor progression in vivo, which suggests that FTO may have an oncogenic role in colorectal cancer." (PMID 36874096, 2023). "In the present study, we show that FTO is expressed in various human colorectal cancer cell lines." (PMID 36874096, 2023). "While we cannot exclude the subtle alteration of internal m6A marks that would have been missed out due to the limit of detection of m6A changes by MeRIP-seq57, our data clearly establishes cap-m6Am residues of mRNA as the main substrate of cytoplasmic FTO in colorectal cancer cells." (PMID 33741917, 2021). "Similarly, FTO is observed as a tumor suppressor in colorectal cancer." (PMID 39192357, 2024). "In addition, FTO can enhance chemotherapy resistance in colorectal cancer." (PMID 37511932, 2023). "Additionally, it has been reported that on a mechanistic level, FTO functions as a tumor suppressor by regulating metastasis-associated protein 1 expression through an m6A-dependent pathway, which promotes metastasis in colorectal cancer under the hypoxia-mediated FTO downregulation." (PMID 38148841, 2023). "Therefore, it can be speculated that ALKBH5, METTL3, and FTO may accelerate the growth of colorectal cancer." (PMID 37511932, 2023). "Moreover, FTO gene upregulation may play a role in colorectal carcinoma cells through phosphatidylinositol-3-kinase (PI3K)/Akt/mammalian target of rapamycin (mTOR) pathway." (PMID 36263301, 2022). "Similar to other tumors, the regulation of m6A modifications in colorectal cancer is equally diverse and complex, and almost all m6A modifiers except METTL14, ZC3H13, METTL3, FTO, ALKBH5, and YTHDF2 promote colorectal carcinogenesis." (PMID 39967906, 2025). "In a word, inhibiting AKT activated ferroptosis through FTO/YTHDF2/GPX4 axis to suppress colon cancer progression, which raised FTO/GPX4 as potential biomarkers and targets in colorectal cancer therapy." (PMID 38102129, 2023). "We found that the FTO inhibitor, CS1 suppressed CRC cell proliferation in 6 colorectal cancer cell lines and in the 5-Fluorouracil resistant cell line (HCT116-5FUR)." (PMID 36874096, 2023). "It has been found that FTO is regulated by miR-1266 in the nucleus and initiates cell signaling molecules STAT3, cyclin D1 and MMPs to promote the development of colorectal cancer." (PMID 35614935, 2022). "In colorectal cancer, Yue and collaborators reveal that AMPKα2 inhibits CRC cell growth and promotes apoptosis through altering FTO." (PMID 35186927, 2022). "Additionally, GSK3 has been shown to have this effect in colorectal cancer, where it prevents the development and spread of CRC by activating the MZF1/c‐Myc axis via FTO." (PMID 40919129, 2025). "miR-96 suppresses AMP-activated protein kinase alpha 2 (AMPKα2), inducing FTO upregulation and subsequent MYC expression enhancement via prevention of its m6A modification, thereby mediating pro-proliferative and anti-apoptotic effects in colorectal cancer." (PMID 40986143, 2025).
colorectal cancer (continued). "Besides, ALKBH5, FTO, METTL3, METTL14, METTL16 and WTAP were detected in a section of colorectal cancer tissue." (PMID 39039912, 2024). "Furthermore, AKT, FTO and GPX4 were expressed at greater levels in cancer than adjacent tissues and found FTO and GPX4 are potential biomarkers in colorectal cancer." (PMID 38102129, 2023). "Importantly, chemoprotection bestowed by FTO silencing extended to FOX treatment (50 μM 5-flurouracil (5-FU) + 1 μM oxaliplatine), another advanced stage colorectal cancer therapy." (PMID 33741917, 2021). "Here the authors show that FTO impedes cancer stem cell-like abilities in colorectal cancer cells through its m6Am demethylase activity, not through internal m6A demethylase activity." (PMID 33741917, 2021). "FTO was proved to be negatively regulated by miR-1266 in colorectal cancer cells, but the effect and mechanism of FTO or miR-1266 on cancer progression was not addressed." (PMID 32209098, 2020). "In addition, one group recently found that FTO is regulated by miR-96, which affects the methylation level of MYC and increase the expression of MYC, thus participating in the pro-proliferative and anti-apoptotic effects of miR-96 in colorectal cancer." (PMID 35614935, 2022). "However, the role of FTO in colorectal cancer has not been fully investigated." (PMID 36874096, 2023). "Additionally, IGF2BP2 decreases MTA1 expression in the absence of FTO, indicating that FTO and IGF2BP2 control MTA1 expression in colorectal cancer via methylation." (PMID 40919129, 2025).
depression (53 papers, 2014 to 2025). "The m6A demethylase FTO is highly expressed in the hippocampus, a brain region consistently implicated in depression." (PMID 40981072, 2025). "Extending beyond depression, downregulated FTO has also been implicated in the pathophysiology of mood disorders comorbid with neuropathic pain (NP)." (PMID 40590504, 2025). "Previous studies demonstrate that depression enhances the effect of FTO variants on BMI, such that individuals with depression have an additional 2.2% increase in BMI for each rs9939609 risk allele (A) compared with psychiatrically healthy individuals." (PMID 39088267, 2024). "Additional studies found that the RNA demethylase FTO, one of the genes associated with depression, was significantly downregulated in the serum of depressed patients and the hippocampus of mice with depression-like behaviors." (PMID 36672884, 2023). "A recent analysis showed that there was an RNA m6A eraser ALKBH5 mutation in Chinese Han people with MDD, while the rs9939609 A mutation in the FTO gene was negatively correlated with depression." (PMID 36009052, 2022). "Additional evidence indicating the role of FTO in learning and behavior includes a study in which mice deficient in FTO were reported to exhibit behaviors consistent with depression and anxiety." (PMID 34095121, 2021). "Therefore, there is a need of further research to investigate the interaction among the FTO gene, BMI loss, and depression decline following LSG." (PMID 39088267, 2024). "The conclusions about the association between FTO and depression may be different when considering the heterogeneity of depression." (PMID 35634463, 2022). "Apart from AD, some genetic variants of FTO have been linked to major depressive disorder (MDD)." (PMID 34039354, 2021). "Supporting the evidence that a FTO genetic variation could have an effect on BMI modulation by mood‐state regulation in patients with BD, an association with FTO variants has also been found in patients with major depressive disorder and eating‐disorders." (PMID 31033179, 2019). "Moreover, FTO deficiency has been shown to reduce anxiety- and depression-like behaviors." (PMID 36118889, 2022). "Furthermore, other work on FTO-deficient mice suggested that FTO could influence anxiety- and depression-like behaviours via alterations in gut microbiota." (PMID 35186031, 2022). "Moreover, FTO polymorphisms were associated with depression/anxiety and psychological distress." (PMID 25265168, 2014). "Ultimately, the FTO–environment interaction leads to depression when it is accompanied by lowered self-esteem, social stigmatisation, or metabolic changes." (PMID 41375608, 2025). "In CRS-induced depression mice that were treated with GRb1, hippocampal FTO expression levels were increased significantly." (PMID 39940841, 2025). "In animal models of depression induced by chronic restraint stress, decreased expression of another demethylase, FTO, in the hippocampus impairs synaptic plasticity, leading to depressive-like behaviors either." (PMID 40590504, 2025). "In depression models, the m6A demethylase FTO has been shown to influence hippocampal memory and stress adaptation." (PMID 40981072, 2025). "In this study, using cadaveric brain samples from MDD patients and a CRS-induced depression mouse model, we identified a key role for the RNA demethyltransferase FTO in regulating ferroptosis." (PMID 39940841, 2025). "FTO is a demethylase of N6-methyladenosine (m6A) enriched in brain neurons, playing an important role in the mechanism of depression." (PMID 38384936, 2024). "Further research has confirmed the neuroprotective role of hippocampal FTO in depression-like behavior through the activation of the CaMKII/CREB signaling pathway, improving hippocampal synaptic plasticity (dendritic remodeling, PSD95, and SYN expression)." (PMID 38656892, 2024). "Evidence links FTO to neuropsychiatric disorders such as Alzheimer’s, Parkinson’s disease, anxiety, depression, and epilepsy." (PMID 39192357, 2024).
depression (continued). "In our study, T allele carriers of FTO rs9939609 had greater SHAPS and PHQ-9 values, suggesting an increased risk of depressive disorder among psoriatic patients." (PMID 38540130, 2024). "These pathways targeted by FTO were previously reported in depression and antidepressant-effects, suggesting that hippocampal FTO mediates, at least in part, depressive-like behaviors through cell-communication pathways." (PMID 37047192, 2023). "Considering that METTL3, METTL14, and WTAP are core components of the methyltransferase complex, and FTO and ALKBH5 are major demethylases, it was reported that METTL3, FTO, and ALKBH5 were implicated in the pathology of depression." (PMID 37175269, 2023). "Next, we performed differential gene analysis of m6A regulators in depression and found that FTO, RBM15B, METTL3, LRPPRC, HNRNPC, ZC3H13, and YTHDF2 were significantly upregulated in depressed rats." (PMID 35480327, 2022). "After administration of the antidepressant fluoxetine, FTO was significantly upregulated, and depression-like behaviors improved, providing further confirmation that FTO is involved in the development of depression." (PMID 35682599, 2022). "A recent study has shown that FTO was significantly downregulated in the serum of patients with major depression and in the hippocampus of mice with depressive-like behavior." (PMID 35682599, 2022). "Our study provided the evidence that FTO was decreased in mice with anxiety- and depression-like behaviors induced by NP, which was reversed by overexpression of FTO in ACC." (PMID 35634463, 2022). "The meta-analyzed results indicate that the effect of FTO genotype on BMI is moderated by depression status." (PMID 35308733, 2022). "FTO expression has been shown to be downregulated in the hippocampus of MDD patients and mouse models of depression, and FTO in mouse hippocampal tissue was shown to induce depressive-like behavior in mice by targeting ADRB2." (PMID 36118889, 2022). "For instance, a recent meta-analysis gave evidence for an interaction effect between the FTO gene, BMI and depression." (PMID 35918662, 2022). "FTO-KO mice were more resistant to stress stimulation, suggesting the vital function of FTO in pathogenesis of depression." (PMID 35945194, 2022). "In UK Biobank we were unable to replicate the previously reported interaction between a SNP in the FTO gene and depression." (PMID 35388897, 2022). "Our study indicates that FTO in the hippocampus mediates depression-like behaviors and that hippocampal FTO can be exploited to serve as a therapeutic target for depression." (PMID 34836959, 2021). "The present study demonstrated that FTO in the hippocampus was critical in mediating depression-like behaviors." (PMID 34836959, 2021). "Knockdown or knockout of Fto in the hippocampus induces depression-like behaviors, whereas overexpression of FTO has antidepressant effects." (PMID 34836959, 2021). "Next, we focused on investigating the mechanism by which hippocampal FTO mediates depression-like behaviors." (PMID 34836959, 2021). "It is conclusive that hippocampal FTO can be exploited to serve as a therapeutic target for depression." (PMID 34836959, 2021). "Here, we report that FTO in the hippocampus mediates depression-like behaviors through RNA demethylase activity." (PMID 34836959, 2021). "The genetic polymorphism of FTO is related to attention-deficit/hyperactivity disorder (ADHD), Alzheimer’s disease and depression." (PMID 31452869, 2019). "Other studies have used a SNP in the FTO gene as a genetic instrument for BMI and identified potential effects of higher BMI on lower psychological distress and a combined depression anxiety symptoms score." (PMID 30707692, 2019). "Suppression of Fto expression in the mouse hippocampus results in depression-like behaviour in adult mice, whereas overexpression of FTO expression rescues the depression-like phenotype, suggesting that FTO is a modulator of depression-like behavioural mechanisms in mice." (PMID 37387537, 2023).